CCL17 (C-C motif chemokine ligand 17)
Diseases named in the same sentence as CCL17 in open-access papers (continued):
Sharing a sentence is not in itself a finding about the gene and the disease.
tumor (continued). "Both CCL22 and CCL17, which are produced by tumor cells, tumor-associated macrophages, and dendritic cells, establish a concentration gradient around the tumor mass and attract CCR4+ Tregs to maintain immunological homeostasis in the tumor vicinity." (PMID 35222362, 2022). "We show that the likelihood of CCR4 blockade therapy response (tumor burden reduction and survival) can be increased by determining the urinary CCL17 concentration or BRAFV595E somatic mutation." (PMID 35131860, 2022). "Taken together, these data demonstrated that CCL17 secretion from lactate-induced M2-like TAMs is linked with the tumor invasion of human PAs." (PMID 33664865, 2021). "High levels of lactate in the TME promote differentiation of tumor-associated macrophages to the M2 subtype, while activated macrophages facilitate tumor invasion through the CCL17/CCR4/mTORC1 signaling axis." (PMID 35047511, 2021). "The number of CCL2+ and CCL17+ TANs was found to be associated with tumor size, microvascular invasion, level of tumor differentiation, and staging." (PMID 34200529, 2021). "According to univariate analysis of clinical data, high CCL17 expression was associated with larger tumor size (P = 0.0438), greater invasion (P = 0.0334), and higher susceptibility to postoperative recurrence (P = 0.0195) in human PAs." (PMID 33664865, 2021). "In the ulcerated tumor, B cells showed increased markers associated with type-2 responses such as CCL17, IL4R, and decreases in interferon-stimulated genes (IFI44L, STAT1, IFITM1, MX1, IRF1)." (PMID 34583709, 2021). "CCL17 is also secreted by immunosuppressive tumor-associated neutrophils (TANs) and cancer-associated fibroblasts." (PMID 34885241, 2021). "CCL17 was reported as a key cytokine in the generation of tumor-associated macrophages, which stimulates EMT and stemness." (PMID 34680267, 2021). "Higher CCL17 expression predicted larger tumor size, greater invasion, and greater susceptibility to postoperative recurrence." (PMID 33664865, 2021). "These protein levels were significantly higher in TANs than in the peripheral blood, and the number of CCL2+ or CCL17+ TANs was associated with tumor size, microvascular invasion, differentiation, and clinical stage." (PMID 34071550, 2021). "TSLP caused the release of CCL17 by tumor cells with recruitment of eosinophils that in turn induced proliferation and restricted tumor cell apoptosis through up-regulation of Ki-67 and Bcl-2, respectively and of proangiogenic factors." (PMID 33042121, 2020). "Tumor-associated neutrophils released cytokine CCL17, which can recruit Treg cells into the tumor microenvironment to affect antitumor immunity." (PMID 33335850, 2020). "Infiltration of Tregs was caused by the interaction between the tumour-producing chemokine CCL17 and receptor CCR4 expressed on Tregs in dogs bearing spontaneous bladder cancer." (PMID 32680511, 2020). "A subpopulation of TAMs isolated from subcutaneous tumor models was shown to secrete CCL17 as a hallmark of M2-like macrophage polarization." (PMID 31681563, 2019). "Conversely, IL-4 induced CCL17, a chemokine associated with Treg recruitment, M2-polarized macrophages, and tumor-associated neutrophils." (PMID 30849228, 2019). "In contrast, exposure to IL-4 and/or IL13 (24h) polarizes them towards pro-tumor M2-macrophage fate (aka tumor associated macrophages or TAMs), as detected by increased expression of the M2-macrophage biomarkers; CCL17 and CCL18 in them (see RT/PCR analysis)." (PMID 29262555, 2017). "While the secretion of CCL22 and CCL17 has been implicated in Treg recruitment to the tumor microenvironment in several studies, the role of these chemokines in the recruitment of Tregs to inflammatory sites during Mtb infection has yet to be addressed." (PMID 23785280, 2013). "Furthermore, increased CCL17 has been associated with higher infiltration and tumour-promoting activity of regulatory T cells (Tregs)." (PMID 40361460, 2025).
tumor (continued). "While CCL17 has been associated with protective roles in myocardia disease, studies in tumour immunology have found that CCL17‐mediated recruitment of Tregs promotes tumour progression and resistance." (PMID 39031979, 2024). "In addition, tumor associated neutrophils recruit macrophages and T regulatory cells that negatively regulate adaptive immunity, promoting progression through the CCL17 pathway." (PMID 37881434, 2023). "Using somatic mutation data of TCGA-LUAD, we found that 1) the tumor mutation burden values of the CCL17 high-expression group were significantly lower than those of the CCL17 low-expression group and 2) the expression levels of CCL17 and the tumor mutation burden values were negatively correlated." (PMID 35321241, 2022). "Tumor gene expression analysis performed 7 days post Imprime dosing showed upregulation of M1 markers, e.g., Nos2, Il12b, and Tnfa, along with downregulation of M2-associated genes including Arg1 and Ccl17." (PMID 35692755, 2022). "Tumor associated macrophages (TAMs) and myeloid suppressor cells (MDSCs) release chemokines, such as CCL17, CCL22, CCL5, CCL6 or CCL28, depending on the tumor type, to attract Tregs expressing the chemokine receptors CCR4, CCR5, CCR10 and CXCR3 from secondary lymphoid tissues to the tumor." (PMID 32937953, 2020). "Interestingly, Treg cells might be recruited to the TME by cytokines such as CCL2 and CCL17 produced by tumor-associated neutrophils, thus promoting the progression of HCC and resistance to Sora." (PMID 39743020, 2025). "In addition, markers increasing from baseline in patients progressing through treatment include CXCL13, CCL17, and reduced clonal T-cell diversity, likely reflecting increasing tumor burden and activation of a Tfh axis previously associated with poor prognosis of lymphocyte-rich HL." (PMID 38934093, 2024). "Tumor-associated leukocytes isolated from lymph node+ BC patients secreted 2- to 5-fold more cytokines than lymph node- patients, with the most increased cytokines being thymus and activation-regulated chemokine (TARC/CCL17), IGF-1, IL-3, TNF-β, IL-5, G-CSF, IL-4, and IL-1α." (PMID 34602858, 2021). "Indeed, the BRAFV595E mutation which is present in 75–87% of canine UC tumors has been shown to be associated with tumor-produced CCL17 and regulatory T cell infiltration in dogs with UC highlighting the potential influence of the tumor immune environment on UC tumor behavior." (PMID 34600548, 2021). "Additionally, tumor cells or tumor‐associated macrophages (TAMs) could also secrete CCL17 and CCL22 which are able to recruit CCR4+ regulatory T cells (Treg)." (PMID 31231980, 2019). "Serum CCL17 levels are positively correlated with skin tumor burden and are significantly higher in patients with tumor-stage MF compared to patients in the patch stage." (PMID 41614909, 2026). "An increased expression of the anti-inflammatory pro-tumor gene Ccl17 was observed only in the RLS40High subgroup, while, in DNase I-treated subgroups, Ccl17 mRNA expression was at the level observed in the healthy control." (PMID 40867260, 2025). "The tumor-promoting role of M2-like macrophages-derived CCL17 in ESCC was investigated from these aspects: cancer cell migratory ability, cancer cell invasive ability and cancer cell stemness characteristics." (PMID 39473097, 2025). "Nevertheless, the tumor-promoting effects of TAMs-derived CCL17 on ESCC development remains uncertain till now." (PMID 39473097, 2025). "In contrast, low-risk genes (CCL17, CXCL8, FOXP3, CCR7) inhibit tumor progression by modulating immune cell infiltration and activity." (PMID 40517358, 2025). "CCL17, produced by cells in the tumor microenvironment, contributes to the recruitment of Th2-polarized malignant T lymphocytes Tregs." (PMID 40861461, 2025). "IL-4 can activate M2-type macrophages, secrete IL-10, TGF-β, and CCL17, thereby inhibiting T cell-mediated anti-tumor immune responses." (PMID 40557160, 2025).
tumor (continued). "Multiple studies have reported that serum CCL17 levels are significantly higher in patients with tumor-stage MF compared to those with patch or plaque lesions." (PMID 40861461, 2025). "Specifically, Bcor−/−; TCL1 malignant cells showed upregulation of Ccl17 and Ccl22 chemokines that attract regulatory T (Treg) and Th2 cells in tumor microenvironment (TME)." (PMID 40113912, 2025). "To analyze the neutrophil properties, we used the following frequently mentioned profiles: pro-tumor anti-inflammatory profile (Mmp9, Vegfa, Arg1, Nos2, Ccl17, Il10) and anti-tumor pro-inflammatory profile (Icam1, Tnfa)." (PMID 40001601, 2025). "They contribute to tumor development through the release of IL-1β, yet also secrete CCL17 to recruit regulatory T cells, facilitating immune evasion, and support angiogenesis." (PMID 41299673, 2025). "TANs have also been shown to secrete CCL17, which attracts regulatory T cells (T-regs) to the tumor site and promotes an immunosuppressive environment that supports tumor growth." (PMID 39941753, 2025). "Tumor cells and tumor-associated macrophages upregulate CCL22 and CCL17, ligands for CCR4, which promote Treg chemotaxis toward the tumor microenvironment." (PMID 41394821, 2025). "Accordingly, we observed that tumor DC2s and moDCs share a similar transcriptome, including the expression of Treg-recruiting genes such as Ccl22 and Ccl17." (PMID 40146036, 2025). "Lentiviral overexpression of murine IL-15 and CCL17 delays CCA tumor progression in a syngeneic transplant model." (PMID 41332325, 2025). "The tumor-promoting effects of M2-like macrophages-derived CCL17 on the malignant behaviors of ECSS was depended on the activation of CCR4/ERK/PD-L1 pathway." (PMID 39473097, 2025). "TAMs secreted CCL17 can promote tumor growth and invasion of human pituitary adenoma and enhance susceptibility to postoperative recurrence." (PMID 39473097, 2025). "They secrete anti-inflammatory cytokines, including IL-10, TGF-β, CCL22, and CCL17, which support immune suppression and aid in tumor progression." (PMID 40867316, 2025). "In this work, for functional experiments, Eca109 cells cultivated in M2-CM were treated with anti-IgG (50 μg/ml) or anti-CCL17 (50 μg/ml) to expound the tumor-promoting effects of M2-like macrophage-derived CCL17 in ESCC." (PMID 39473097, 2025). "The tumor-promoting effects of M2-like macrophages-derived CCL17 on ECSS was depended on the activation of CCR4/ERK/PD-L1 pathway." (PMID 39473097, 2025). "GM-CSF blockade reduced the expression of GM-CSF downstream genes Ccl6 and Ccl17, asserting treatment efficacy, and substantially curbed tumor growth, leading to a significant increase in animal survival." (PMID 38519484, 2024). "HCC-derived CCL17 exhibited a robust relationship with CD73, present on both tumor and stroma cells, indicating its significant association with heightened CD73 expression in the TME." (PMID 38914802, 2024). "Specifically, 6 Gy treatment resulted in increased CD8+ T-cell infiltration at the tumor site, which correlated with elevated expression of the chemokine, CCL17." (PMID 39877375, 2024). "CCL22 produced by tumor derived macrophages and CCL17 regulate the infiltration of Tregs into the tumor sites." (PMID 38571964, 2024). "Patients with lower levels of CCL2+ or CCL17+ cells in their tumours have shown longer survival times compared to those with higher numbers of these cells." (PMID 39031979, 2024). "CCL17, also known as thymus and activation-regulated chemokine (TARC), is highly expressed in pro-tumor N2 TANs and at a very low level in anti-tumor N1 TANs." (PMID 39061147, 2024). "Previous in vivo studies have demonstrated that CCL17 enhances T-cell infiltration into the tumor microenvironment." (PMID 39877375, 2024). "ELISA analysis of irradiated progeny cell supernatants revealed an overall increase in CCL17 secretion compared to unirradiated tumor cells." (PMID 39877375, 2024).
tumor (continued). "Tumor-associated neutrophils (TANs) produced chemokines such as CCL2 and CCL17, which later recruited TAMs and Tregs and promoted tumor growth in HCC." (PMID 38362156, 2024). "To validate these findings, we performed immunohistochemistry and multiple immunofluorescence staining for CD8 and CCL17 on tumor sections from the initial mouse group." (PMID 39877375, 2024). "Using the TIMER database, we analyzed CCL17 expression across all TCGA tumor types, focusing on the contrast between tumor tissues and adjacent normal tissues." (PMID 39877375, 2024). "Upon the polarization of neutrophils via TGFβ, pro-tumor N2 phenotype showed a high expression of CCL17, ARG1, and CXCL14." (PMID 39061147, 2024). "As lactic acid levels increase in the TME, tumor-associated macrophages differentiate into M2 subtypes, while activated macrophages promote tumor invasion through the CCL17/CCR-4/Mtorc1 signaling axis." (PMID 37781694, 2023). "Tumor cells and tumor-associated macrophages secrete the chemokines CCL22 and CCL17, which attract CCR4+ Treg cells." (PMID 37107673, 2023). "On the other hand, the high transcriptional overexpression of CCL17, also called TARC, seems to have a complex effect on tumor immunity." (PMID 37762335, 2023). "Another indirect effect of type I IFN-mediated Treg suppression occurs when intratumoral IFNα delivery downregulates tumor expression of CCL17 that trafficks Tregs to tumor centers." (PMID 37304294, 2023). "CCL17 is also able to modulate the tumor-supportive environment by recruiting regulatory T-cells (Tregs) and T helper 17 cells (Th17), which can suppress anti-tumor immune response." (PMID 36661524, 2023). "Clinically, the anti-angiogenic treatment sorafenib—one of the first-line agents to treat HCC—is associated with an increase in TANs that produce CCL2 and CCL17, which can establish immunosuppressive niches within the TME to promote tumor cell survival." (PMID 38139412, 2023). "NPC chemokine expression was not exclusive to EBER1+ cells and it was difficult to determine the fraction of CCL17/22 expression that was tumor-extrinsic." (PMID 35025968, 2022). "It indicates that with the decrease of CCL17 expression, the tumor stage increases, and the decrease of CCL17 expression is unfavorable to patient survival." (PMID 35321241, 2022). "Here, we show some EBV+ tumor cells express high levels of the chemokines CCL17 and CCL22 both in vitro and in vivo and that this expression mirrors the expression levels of expression of the EBV LMP1 gene in vitro." (PMID 35025968, 2022). "TAMs produce CCL17 by the stimulation of RANKL derived from Paget cells to recruit Tregs in the tumor microenvironment, maintaining the immunosuppressive microenvironment in EMPD." (PMID 35409404, 2022). "CCL17 is an important chemokine that plays a vital immunomodulatory role in the tumor microenvironment (TME)." (PMID 35321241, 2022). "The C-C motif chemokine ligands, CCL17, CCL18, and CCL22, which are secreted from activated TAMs, are associated with the enlargement of tumor size and the promotion of tumor metastasis, and the recruitment of Treg cells." (PMID 35955737, 2022). "C–C Motif Chemokine Ligand-17 (CCL17) is a tumor promoting protein that activates regulatory T cells thereby inhibiting the antitumor response." (PMID 36572780, 2022). "Meanwhile, immunohistochemical staining of the tumor tissue of another 65-year-old female patient with LUAD showed some degree of protein expression of both CCL17 and CD79B (naive B cells marker molecule)." (PMID 35321241, 2022). "Expression of CCL17 in LUAD was positively correlated with the proportion of tumor-infiltrating lymphocytes, immunostimulators, and major histocompatibility complexes using the TISIDB databases." (PMID 35321241, 2022). "CCR4, which binds to macrophage-derived chemokine (MDC/CCL22) and thymus- and activation-regulated chemokine (TARC/CCL17), is predominantly expressed by tumor-associated Treg cells." (PMID 35222362, 2022).
tumor (continued). "The FOXP3+CCR4+ Tregs from breast cancer patients’ peripheral circulation infiltrate tumor site in response to TME-secreted CCL17 and CCL22." (PMID 35222362, 2022). "This emphasised the key association of D14 neutrophils, PD-L1+ myeloid cells and Ly6Cintermediate monocytes with CT26 tumour size, and a more distant relationship with D7 myeloid cells, CCL17, CXCL1, CCL2, CXCL10 levels, and D14 IL-10 level." (PMID 35226704, 2022). "CCL22 and CCL17 were significantly downregulated cytokines in PRAME-deleted tumor samples, emphasizing the role of PRAME in TME crosstalk." (PMID 35380993, 2022). "Taken collectively, an increase in CCL17 levels in Pan02 tumor-bearing mice shows the accumulation of innate immunity cells and fibroblasts forming significant extracellular matrix, as supported by the histological results." (PMID 36286054, 2022). "Among CCL chemokines, CCL2, 3, 4, 7, and 8 were significantly less secreted by tumor tissues, while CCL17, CCL20, and CCL22 were secreted in higher concentrations in tumor as compared to juxta-tumor tissues." (PMID 36539890, 2022). "Elevated levels of G-CSF, IL-6 and CXCL13, and B cell counts were associated with 4T1 growth, whereas CCL17, CXCL10, total myeloid cells, CCL2, IL-10, CXCL1, and Ly6Cintermediate monocytes were associated with CT26 tumour development." (PMID 35226704, 2022). "For BCC, studies have revealed the presence of high concentration of T-regs, not only in TME, but also in the tumor bordering skin, chemoattracted by different chemokines, for example CC chemokine ligand 17, 18 and 21 (CCL17, CCL18 e CCL21)." (PMID 35775005, 2022). "Immunohistochemical staining of the tumor tissue of one 51-year-old female LUAD patient showed some degree of protein expression of both CCL17 and CD3G (CD4/CD8+ T cell marker molecule)." (PMID 35321241, 2022). "Tumour cells or infiltrating innate leukocytes release chemokines such as CCL17 and CCL22 to promote the migration of thymic Tregs expressing receptors such as CCR4, CCR5, and CCR8 from the secondary lymphoid tissues to the site of tumour." (PMID 35493450, 2022). "Although the experiments reported here and mechanistic studies show how EBV-derived LMP1 can lead to increased chemokine expression, the mechanism for the tumor-extrinsic increase in CCL17/22, shown here in a variety of settings, is less clear." (PMID 35025968, 2022). "Immunohistochemical staining of the tumor tissue of one 64-year-old female LUAD patient showed some degree of protein expression of both CCL17 and CD4 (CD4+ T cell marker molecule)." (PMID 35321241, 2022). "In conclusion, we have shown that CCL17 attenuates tumor immunity by increasing the levels of Tregs and Th2 cells, while it decreases MDSCs through CXCL17 reductions." (PMID 33670758, 2021). "Taken together, these results demonstrated that CCL17 secreted by M2-like TAMs promotes tumor invasion by activating the mTORC1 signaling pathway." (PMID 33664865, 2021). "In a similar study it was shown that 4T1 cells in the primary tumor can enhance metastasis in the lungs by inducing the expression of TARC/CCL17 and MDC/CCL22 genes." (PMID 33777801, 2021). "In fact, TANs in tumour-bearing mice produced CCL17 to provoke the infiltration of Tregs into tumour parenchyma, thus potentiating tumour progression and emerging as ideal targets for anti-tumour therapy." (PMID 33917287, 2021). "•Knockdown of the long form prolactin receptor reduces Treg recruitment to tumors by reducing tumor parenchymal production of CCL-17." (PMID 34375938, 2021). "Histologically, the occupied colony area of tumor cells was significantly larger in CCL17 TG mice than in WT mice." (PMID 33670758, 2021). "Tumor microenvironment components secrete immunosuppressive chemokines, such as CCL17 and CCL22, to attract Treg cells." (PMID 33648605, 2021).